CXCR1 (C-X-C motif chemokine receptor 1)
Diseases named in the same sentence as CXCR1 in open-access papers (continued):
Sharing a sentence is not in itself a finding about the gene and the disease.
melanoma (continued). "Moreover, CXCR1 and CXCR2 antagonist are also used to treat human melanoma, lung, breast, and pancreatic cancer growth by inhibiting tumor cell proliferation and suppression of angiogenesis and metastasis." (PMID 28484461, 2017). "Recent reports have also described CXCR1 expression in all melanoma cases, irrespective of the stage and grade, and modulation of CXCR1 expression and/or activity has been shown to regulate malignant melanoma growth, angiogenesis, and metastasis." (PMID 27682863, 2016). "Previous studies reported that melanoma cells express high levels of IL8 and CXCL1 and their receptors CXCR1/2 and that IL8/CXCL1 signaling directly promotes cell migration of tumor cells, which may be relevant to tumor invasion and metastasis." (PMID 22719918, 2012). "CXCR1 or CXCR2 were stably overexpressed in human melanoma cell lines, SBC-2 (non-tumourigenic) and A375P (low-tumourigenic) exhibiting low endogenous expression of receptors." (PMID 19401689, 2009). "Hence, once again our data emphasise the importance of CXCR1 and CXCR2 expression in melanoma cells." (PMID 19401689, 2009). "In this study, we hypothesised that CXCR1 and CXCR2 regulate melanoma tumour growth and progression." (PMID 19401689, 2009). "Similar results were observed in SBC-2-transfected cells (data not shown) Together, these results demonstrate that overexpression of CXCR1 or CXCR2 in SBC-2 and A375P melanoma cells leads to CXCL-8-induced activation of ERK1/2 MAP kinase, which facilitates increased cell growth and motility." (PMID 19401689, 2009). "We have performed in vitro and in vivo functional assays to provide direct evidence for multiple overlapping roles of CXCR1 and CXCR2 in melanoma growth, tumourigenesis, motility and invasion in two cell line models (SBC-2, non-tumourigenic and A375P, low-tumourigenic)." (PMID 19401689, 2009). "Therefore, the fact that tumour growth was induced and enhanced by overexpression of CXCR1 or CXCR2 in melanoma cells suggests the importance of CXCR1 and CXCR2 as key determinants of melanoma tumourigenesis and growth." (PMID 19401689, 2009). "The chemotactic response of melanoma cells to IL-8 was mediated by CXCR1, and the mitogenic activity of IL-8 was mediated by both CXCR1 and CXCR2 in colon cancer, but only by CXCR1 in monocytes." (PMID 15545974, 2004). "Importantly, we show that the CXCR1/CXCR2 antagonist, SX-682, accomplishes a similar reduction in melanoma tumor burden, establishes an anti-tumor immune microenvironment, and significantly alters the transcriptional profile of melanoma cells when delivered during the transformation process." (PMID 37270599, 2023). "Aside from its direct effect on melanoma cells, CXCL8, along with other ligands of CXCR1 and CXCR2, namely CXCL1-3 and CXCL5-7, recruit innate cells, most notably neutrophils, which express the receptors CXCR1 and CXCR2 and are the “first responders” to tissue injury and damage." (PMID 34830780, 2021). "Studies with neutralizing antibodies to either CXCR1 and CXCR2 showed inhibition of MC proliferation and invasive potential whereas in athymic nude mice oral administration of CXCR1/2 antagonists, inhibited the growth and angiogenesis of implanted human melanoma tumors." (PMID 35011682, 2021). "Collectively, these studies outlined the pre-requisites of the successful CXCR1/2 inhibition on malignant cells and demonstrated multifactorial effects of Ladarixin on cutaneous and uveal melanomas, suggesting therapeutic utility of LDX in treatment of various melanoma types." (PMID 28129639, 2017). "This is not surprising because melanoma cells can interact with endothelial cells in many ways and can trigger multiple pathways leading to gap formation at the same time as opposed to isolated activation of the CXCR1 and CXCR2 receptors by IL-8." (PMID 28393886, 2017).
melanoma (continued). "Overexpression of the receptors CXCR1 and CXCR2 in human melanoma cells increased cell proliferation and invasion in vitro and significantly enhanced tumor growth in vivo, thus demonstrating the importance of these receptors in melanoma tumor growth and progression." (PMID 24259307, 2013). "However, we did not observe a difference in ERK1/2 phosphorylation between melanoma cells expressing CXCR1 or CXCR2, which further suggests the involvement of both receptors in the MAPK pathway." (PMID 19401689, 2009). "However, the functional significance of CXCR1 and CXCR2 and its ligand CXCL-8 in melanoma progression remains unclear." (PMID 19401689, 2009). "CXCR1 and CXCR2 mRNA exhibited a trend toward increased expression in melanoma compared to nevi, but these differences were not statistically significant." (PMID 37270599, 2023). "CXCR1 and CXCR2 are overexpressed on melanoma cells, but their precise functional role in human melanoma progression is not well established." (PMID 19401689, 2009).
lung carcinoma (32 papers, 2004 to 2025). "It was demonstrated that CCR2 and CXCR1 signaling played a critical role in the cross-talk between tumor-associated macrophage and lung cancer cells." (PMID 35529878, 2022). "Furthermore, CXCR1/2 expression was found to be reduced in lung cancer patients, and these receptors are linked to neutrophil and macrophage infiltration." (PMID 36164329, 2022). "This study evaluated the effects of CXCR1/2 antagonism by G31P, a CXC motif chemokine ligand 8 (CXCL8)-mutated peptide, alone or in combination with gefitinib, on lung cancer growth and chemotherapy-induced pulmonary inflammation." (PMID 41425704, 2025). "Primary cultured cells from samples of patients with MPE from PADC, along with a commonly utilized lung cancer cell line, were employed to examine the role of IL-8 and its receptor, CXCR1, through comparative analysis." (PMID 38891100, 2024). "The mRNA expression of CXCL-8, CXCR1 was inhibited in a study comparing lung cancer cells with a control group in terms of migration and invasion during epithelial to mesenchymal transition." (PMID 36926328, 2023). "In the context of breast and lung cancer, combined SX-682, an bioavailable small-molecule inhibitor of CXCR1 and CXCR2, and anti-PD-1/PD-L1 can achieve best tumor control in murine model." (PMID 35372515, 2022). "CXCR1/2 and their ligands are both expressed by lung cancer cells, and receptor inhibition with an antagonist decreased migration and enhanced apoptosis in vitro and suppressed tumor growth, metastasis, and angiogenesis in a mouse xenograft model." (PMID 36118530, 2022). "In vivo, tumor development, metastatic events, and angiogenesis were all dramatically reduced following CXCR1/2 suppression with G31P in a study with an orthotopic xenograft mouse model of human lung cancer." (PMID 36164329, 2022). "Two lung cancer cell lines (H460 and A549) were first exploited to determine the gating strategy for CXCR1." (PMID 30883740, 2019). "We also studied the possible interaction between MH and two other cytokine receptors with important pro-tumorigenic roles in breast and lung cancer cells, namely IL-11R, which is a member of the IL-6R family, and the distinct IL-8R (CXCR1) chemokine receptor." (PMID 31491838, 2019). "The effects of REEPs on CXCR1-related cellular responses were analyzed in heterologous cells and lung cancer cells expressing endogenous CXCR1." (PMID 27966653, 2016). "Nevertheless, the regulation of CXCR1 signaling by REEPs likely influenced the growth and metastasis of the lung cancer cells." (PMID 27966653, 2016). "Taken together, these findings provide further evidence that CXCR1/2 and their ligands are upregulated in lung cancer." (PMID 26087179, 2015). "Certain studies conducted in ovarian and lung cancer cell lines showed that the CXCR1/2 receptor/ligand pathway transactivates EGFR, promoting the downstream activation of MAPK signaling and mediating cell proliferation and survival." (PMID 23420470, 2013). "Our results showed that all the lung cancer cell lines tested expressed CXCR1 and CXCR2 except A549." (PMID 15545974, 2004). "Our results show that CXCR1 is the major receptor that mediates the mitogenic function of IL-8 in lung cancer." (PMID 15545974, 2004). "Moreover, in animal models of breast and lung cancers, the production of CXCR1/2 agonists by tumor cells was associated with high NET levels in the tumors, and NET levels were decreased after CXCR1/2 blockade." (PMID 36555469, 2022). "Finally, several genes, such as ADRA2A, P2RY12, ADORA1, CXCR1, and CXCR4, were predicted as potential druggable genes for ALI with GGPPS1-knockout, and were associated with the prognosis of lung cancers." (PMID 35795000, 2022). "In A549 lung cancer cells, which endogenously express CXCR1, the depletion of REEP5 and REEP6 significantly reduced growth and invasion by downregulating IL-8-stimulated ERK phosphorylation, actin polymerization and the expression of genes related to metastasis." (PMID 27966653, 2016).
lung carcinoma (continued). "Likewise, IL-8 was reported to induce stemness and EGFR inhibitor resistance in lung cancer, and CXCR1/2 inhibition decreased tumor growth, metastasis, and angiogenesis of lung cancer xenografts." (PMID 27348007, 2016). "In agreement with those previous reports, we have demonstrated here a robust increase of IL-8 secretion and upregulation of CXCR1 in erlotinib-resistant lung cancer cells, compared to their parental counterparts, regardless of the mutational status of EGFR or KRAS." (PMID 27248176, 2016). "Therefore, targeting both IL-8 production and CXCR1 expression may contribute to control of lung cancer progression, invasion and metastasis through both angiogenic and mitogenic properties of IL-8." (PMID 15545974, 2004). "Reduced mRNA expressions of urokinase plasminogen activator (uPA) and inhibited mRNA expression of CXCL-8, CXCR1, ß-catenin connection to migration and invasion of EMT in lung cancer cells." (PMID 36926328, 2023). "Interestingly, REEP5 and REEP6 activate interleukin-8 (IL-8)/CXC chemokine receptor 1 (CXCR1, a G-protein coupled receptor) signaling to promote tumor cell proliferation/migration, angiogenesis, and macrophages/neutrophils recruitment in the tumor microenvironment in lung cancer." (PMID 37238941, 2023). "We report increased mRNA levels of CXCR1 and CXCR2 in human lung cancer tissues compared to normal counterparts." (PMID 26087179, 2015). "In the present study, we report that a number of human lung cancer cell lines, as well as freshly-resected tumor tissues from cancer patients, express both CXCL8 receptors CXCR1/2, which are consistent with previous studies." (PMID 26087179, 2015). "We also compared mRNA levels of CXCR1 and CXCR2 in lung cancer and normal tissues from same patient (a group of 8)." (PMID 26087179, 2015). "Our results suggest that G31P blockage of CXCR1 and CXCR2 can inhibit human lung cancer cell growth and metastasis, which offers potential therapeutic opportunities." (PMID 26087179, 2015). "Using the histone deacetylase inhibitor (HDACi), Trichostatin A (TSA), an induction of CXCL8 and CXCR1/2 in both the normal (HBEC4) and lung cancer cell lines (A549 and SKMES-1), with a concomitant decrease in CXCL1–3 (SKMES-1, p<0.05) was observed." (PMID 21298036, 2011). "The induction of CXCL8 was significant in HBEC4 and SKMES-1 (p<0.05), as was the increase in CXCR1 and CXCR2 in both the lung cancer cell lines (A549 - p<0.05, SKMES-1 – p<0.01) and CXCR1 in HBEC4 (p<0.05)." (PMID 21298036, 2011). "In this study, we investigated the expression of IL-8 and its receptors, CXCR1 and CXCR2, in a panel of NSCLC and SCLC cell lines and characterised the mitogenic role of IL-8 in lung cancer growth." (PMID 15545974, 2004). "Interestingly, lung cancer cells surviving treatment with chemotherapeutic drugs in SCID mice propagated with CSCs-like characteristics and expressed elevated levels of CXCR1/2." (PMID 25871388, 2015). "Therefore, our in vivo and in vitro data are consistent, which together suggest that CXCR1/2 antagonism by G31P inhibits the activation of MAPK and AKT signaling pathways that play pivotal roles in lung cancer progression." (PMID 26087179, 2015). "On the basis of above information, we hypothesized that inhibition of CXCR1 and CXCR2 by G31P might attenuate tumorigenesis of lung cancer." (PMID 26087179, 2015). "The involvement of IL-8, CXCR-1 and CXCR-2 has been extensively investigated in different diseases such as pyelonephritis, hepatitis B, rapid disease progression of HIV-1+, lung diseases, such as chronic obstructive pulmonary disease and asthma, bronchiectasis, systemic sclerosis and lung cancer." (PMID 22051099, 2011). "In addition, a joint targeting of CXCR1/2, TGF-β1, and PD-L1 using the CXCR1/2 inhibitor SX-682 and bintrafusp alfa also reduces EMT, enhances the infiltration of effector T cells and promotes the blockade of granulocytic myeloid cells in breast and lung cancer mouse models in vivo." (PMID 33114183, 2020).
lung carcinoma (continued). "However, since CXCR1 is highly expressed in A549 cells following exposure to DNA methytransferase inhibitors, inflammatory circuits that regulate promoter demethylation, as observed for IL6 signaling, may play an important role for controlling the IL8/CXCR1 responsiveness in lung cancers." (PMID 23935876, 2013). "Zhu found that cell proliferation was significantly reduced by anti-CXCR1 antibody but not by anti-CXCR2 antibody and concluded that the mitogenic function of CXCL8 in lung cancer is mediated mainly by CXCR1 receptor." (PMID 20429924, 2010). "Since the expression of CXCR1 and CXCR2 has not been studied in lung cancer cells, we next examined the expression of these receptors on cell surface by flow cytometry." (PMID 15545974, 2004). "CXCR1 and CXCR2 were found on a variety of tumour cells, but have not been reported in lung cancer." (PMID 15545974, 2004).
ovarian carcinoma (30 papers, 2004 to 2025). A malignant neoplasm originating from the surface ovarian epithelium. "To further determine whether the IL‐8 and its receptors were associated with prognosis of patients with ovarian cancer, we subjected the IL‐8, CXCR1 and CXCR2 to survival analysis using the online database (Gene Expression Profiling Interactive Analysis)." (PMID 31793192, 2020). "Aberrant upregulation of CXCR1/2 is attributed to augmented tumor progression in ovarian cancers, evincing that GROα mediates the oncogenic capacities of cancer invasion and migration by interacting with CXCR1/2 in OvCa." (PMID 36624516, 2023). "IL-8 and its receptor (CXCR1) are upregulated in ovarian cancer cells and mediate homing, migration, and adhesion of ovarian cancer cells." (PMID 34751020, 2022). "By contrast, metastases of ovarian cancer to omentum involve predominantly CXCR1 and CXCR4 is necessary for leukemic cells dissemination to SAT and VAT." (PMID 33671469, 2021). "It is a rather promiscuous interleukin which can dock to different receptors in an autocrine or paracrine fashion, among which CXCR1 is the most prominent in ovarian carcinoma cell lines." (PMID 33658617, 2021). "To investigate the possible role of IL‐8 in ovarian cancer, we exogenously activated or inhibited IL‐8 effect in ovarian cancer cells using IL‐8 or Reparixin (inhibitor of both IL‐8 receptors CXCR1, CXCR2)." (PMID 31793192, 2020). "CAR-NK cells have also been genetically modified to express the chemokine receptor CXCR1 leading to improved trafficking and anti-tumor responses in ovarian carcinoma xenografts in mice." (PMID 33371456, 2020). "MMP1-protease-activated receptor-1 (PAR1)-CXCR1/2 paracrine pathways have been suggested as new targets for ovarian cancer therapy involving peritoneal metastasis." (PMID 32780245, 2020). "These infiltrated MSCs were described as having a role to play in ovarian cancer progression by releasing IL-6, CXCR1/2 ligands (CXCL1, CXCL2, and IL-8), and related cytokine leukemia inhibitory factor (LIF)." (PMID 31547627, 2019). "Activation of MMP-1-PAR1 induces the secretion of interleukin-8 and growth related oncogene α from ovarian cancer cells, which act on endothelial chemokine CXCR1/2 receptors leading to endothelial cell proliferation, tube formation and cancer cell invasion." (PMID 29393911, 2018). "Additionally, C-X-C motif chemokine ligand 8 (CXCL8) was identified as being highly expressed in peritoneal MQs from the ascites of ovarian cancer patients and was positively correlated with C-X-C chemokine receptor 1/2 (CXCR1/2) expression in tumor cells." (PMID 39937005, 2025). "To evaluate whether CXCL8-mediated ovarian cancer cell invasion involves TRIM46 upregulation, we pre-treated ovarian cancer cells with reparixin, a CXCR1/2 inhibitor." (PMID 39937005, 2025). "A large number of studies have shown that the ligand IL-8 of CXCR1/CXCR2 is abnormally increased in the plasma of patients with ovarian malignant tumors and is positively correlated with the clinical stage and pathological type of epithelial ovarian tumor (EOC)." (PMID 33829065, 2021). "Furthermore, the level of IL‐8 and its receptors CXCR1 and CXCR2 expression were associated with ovarian cancer stage, grade and lymph node metastasis." (PMID 31793192, 2020). "The activation of MMP1-PAR1 induces the secretion of angiogenic factors of interleukin 8 (IL-8) and growth-regulated oncogene-alpha from ovarian carcinoma cells, which act on endothelial CXCR1/2 receptors in a paracrine manner, leading to endothelial cell proliferation, tube formation and migration." (PMID 28538838, 2017). "Our recent studies in endometrial and ovarian cancer suggested that CXCL1 and/or CXCL8 secreted by human cancer cells and signalling via their receptors CXCR1 and/or CXCR2 could be implicated in human ASC migration." (PMID 27241286, 2016).